GNAT2 (G protein subunit alpha transducin 2)
Description:
Guanine nucleotide-binding proteins (G proteins) are involved as modulators or transducers in various transmembrane signaling systems. Transducin is an amplifier and one of the transducers of a visual impulse that performs the coupling between rhodopsin and cGMP-phosphodiesterase.
Synonyms: GNATC; ACHM4; HG1D
Tractability: Antibody: its Gene Ontology location is reachable by antibodies, with high confidence. PROTAC: ubiquitination databases record sites on it.
Gene: Protein-coding gene on chromosome 1 (109,601,407 to 109,619,929, reverse strand). Ensembl gene ENSG00000134183.
Subcellular location: Cell projection, cilium, photoreceptor outer segment; Photoreceptor inner segment
Pathways (Reactome):
Signal Transduction: Ca2+ pathway; G alpha (i) signalling events
Gene Ontology:
Molecular function: G protein activity; G protein-coupled photoreceptor activity; G protein-coupled receptor binding; G-protein beta/gamma-subunit complex binding; GTP binding; GTPase activity; guanyl nucleotide binding
Biological process: detection of light stimulus involved in visual perception; transducin-mediated opsin signaling pathway; visual perception; adenylate cyclase-modulating G protein-coupled receptor signaling pathway; detection of chemical stimulus involved in sensory perception of bitter taste; G protein-coupled receptor signaling pathway; phototransduction; positive regulation of cytosolic calcium ion concentration; response to light intensity; signal transduction
Cellular component: cone photoreceptor disc membrane; photoreceptor inner segment; photoreceptor outer segment; heterotrimeric G-protein complex; photoreceptor outer segment membrane; plasma membrane; membrane; synapse
Genetic constraint (gnomAD): Loss-of-function variants: 18 observed, 22.7 expected, observed/expected ratio (o/e) 0.79, 90% interval 0.55 to 1.18. The upper end of that interval is the gene's LOEUF score, 1.18, which puts it in group 5 of 6, group 1 being the genes least tolerant of losing a copy. Missense variants: 155 observed, 214.72 expected, observed/expected ratio (o/e) 0.72, 90% interval 0.63 to 0.82. Synonymous variants: 65 observed, 77.05 expected, observed/expected ratio (o/e) 0.84, 90% interval 0.69 to 1.04.
Homologues: Orthologues: chimpanzee GNAT2 (100% identical), macaque GNAT2 (99% identical), rabbit GNAT2 (97% identical), dog GNAT2 (96% identical), mouse Gnat2 (96% identical), rat Gnat2 (95% identical), pig GNAT2 (94% identical), zebrafish gnat2 (81% identical), tropical clawed frog gnat2 (79% identical), Drosophila melanogaster Galphai (64% identical), Caenorhabditis elegans gpa-16 (57% identical), Caenorhabditis elegans gpa-4 (53% identical), and 13 more. Paralogues in human: GNAT1 (82% identical), GNAT3 (80% identical), GNAI2 (70% identical), GNAI1 (69% identical), GNAI3 (69% identical), GNAO1 (61% identical), GNAZ (57% identical), GNAQ (52% identical), GNA11 (51% identical), GNA14 (50% identical), GNAL (44% identical), GNAS (44% identical), and 3 more.
Diseases named in the same sentence as GNAT2 in open-access papers:
GNAT2 is named in the same sentence as 21 diseases in open-access papers, as found by Europe PMC text mining. Sharing a sentence is not in itself a finding about the gene and the disease. The quoted sentences say what the papers report.
achromatopsia (27 papers, 2008 to 2025). Achromatopsia (ACHM) is a rare autosomal recessive retinal disorder characterized by color blindness, nystagmus, photophobia, and severely reduced visual acuity due to the absence or impairment of cone function. "Five individuals were recruited for experimental electroretinograms (ERGs), including three healthy participants (aged 21 to 47 years), one patient with VAD (aged 70 years), and one patient with GNAT2-associated achromatopsia (aged 43 years)." (PMID 40938071, 2025). "GNAT2, encoding the α-subunit of cone transduction, causes achromatopsia with relatively preserved cone mosaic and structure on retinal imaging and presents with variable refractive error." (PMID 40535564, 2025). "Bi‐allelic variants in GNAT2 (which encodes the alpha subunit of cone transducin) cause achromatopsia." (PMID 40013354, 2025). "Patients with GNAT2‐associated achromatopsia can have relative preservation of cone structure on retinal imaging." (PMID 40013354, 2025). "GNAT2 is an essential component of the cone phototransducation pathway and pathogenic variants in GNAT2 lead to achromatopsia." (PMID 33435268, 2021). "Mutations in GNAT2 have been observed in patients with achromatopsia, and some of these mutations map to the switch domains." (PMID 32315379, 2020). "The alpha subunit of transducin is encoded by GNAT2, and evidence shows that GNAT2 is involved in diseases such as achromatopsia and oligocone trichromacy." (PMID 28484645, 2017). "More recently, a third gene, GNAT2, was implicated in achromatopsia and was mapped to locus ACHM4 on chromosome 1p13." (PMID 18636117, 2008). "Mutations in CNGA3, CNGB3, and GNAT2 have been associated with the majority of studied cases of achromatopsia." (PMID 18636117, 2008). "Mutations in GNAT2 account for approximately 2% of achromatopsia cases." (PMID 39273686, 2024). "In humans, mutations in Gnat2 are associated with achromatopsia." (PMID 32315379, 2020). "Currently, six genes that cause achromatopsia have been discovered, including CNGA3, CNGB3, GNAT2, PDE6C, PDE6H and ATF6." (PMID 38298913, 2024). "We identified variants believed to be disease causing in five of the known achromatopsia genes: CNGA3; CNGB3; GNAT2; PDE6C and PDE6H; and novel variants were identified in CNGB3 and PDE6C." (PMID 36980963, 2023). "Achromatopsia (OMIM:216,900), also called rod monochromatism, characterized by dysfunction of the cone photoreceptors was observed in 3 consanguineous families displaying mutations in CNGA3, CNGB3 and GNAT2, respectively." (PMID 35551639, 2022). "Pathogenic variants in six genes (CNGA3, CNGB3, GNAT2, ATF6, PDE6C, and PDE6H) have been identified in humans with achromatopsia (OMIM 216900)." (PMID 34830323, 2021). "There are several gene therapies reported in achromatopsia animal models: sheep, and mouse models with CNGA3-related achromatopsia, mouse and canine models with CNGB3 mutations, and a mouse model with a genetic defect in the GNAT2 gene." (PMID 32953936, 2020). "Naturally occurring achromatopsia based on mutations in other genes have been described in Awassi sheep (CNGA3) and in mice (CNGA3, GNAT2 and PDE6C)." (PMID 23601474, 2013). "Achromatopsia is caused by sequence variants in CNGA3, CNGB3, GNAT2, PDE6H, PDE6C, and ATF6." (PMID 39273686, 2024). "GNAT2 encodes the cone version of α-transducin, and mutations in GNAT2 result in complete achromatopsia – i.e. no cone function at all – incomplete achromatopsia or extreme red-green color blindness (protanopia)." (PMID 25650393, 2015). "Achromatopsia results from mutations in one of three genes: cyclic nucleotide-gated channel, alpha-3 (CNGA3); cyclic nucleotide-gated channel, beta-3 (CNGB3); and guanine nucleotide-binding protein, alpha-transducing activity polypeptide 2 (GNAT2)." (PMID 18636117, 2008).
achromatopsia (continued). "Pathogenic variants in different genes such as CNGA3, CNGB3, GNAT2, PDE6H, ATF6 and PDE6C have been reported to be relevant to COD, cone-rod dystrophy (CORD) and achromatopsia (ACHM) diseases." (PMID 38956522, 2024). "Defects in Gnat2 cause achromatopsia, or a lack of color vision." (PMID 39337887, 2024). "The similar clinical presentation between familial achromatopsia in humans and bovine recessive day-blindness led to the hypothesis that a protein-changing variant within CNGA3, CNGB3, GNAT2, ATF6, PDE6C, and PDE6H would be associated with achromatopsia of Original Braunvieh calves." (PMID 34830323, 2021). "Mutations in CNGA3 (MIM#600053), CNGB3 (MIM#605080), GNAT2 (MIM#139340), and PDE6C (MIM#600827) have been detected in four probands with OT, which all encode cone phototransduction pathway proteins, suggesting a pathomechanistic overlap with achromatopsia (ACHM)." (PMID 28829391, 2017).
cone-rod dystrophy (4 papers, 2008 to 2024). Inherited retinal dystrophies that belong to the group of pigmentary retinopathies. "The genes involved in cone degeneration, CNGB3, CNGA3 and GNAT2, and the genes involved in cone-rod dystrophy, ABCA4, RDH5, Cord8, Cord9, RPGRIP1, GUCY2D and CRX, were all excluded from being involved in the cone-rod dystrophy described in this family of SWHD." (PMID 18593457, 2008). "Three of the genes, CNGB3, CNGA3 and GNAT2, involved in cone degeneration and seven genes and loci, ABCA4, RDH5, CORD8, CORD9, RPGRIP1, GUCY2D and CRX, reported to be involved in cone-rod dystrophies were studied." (PMID 18593457, 2008). "Additionally, a mouse knockout model of BBS5 developed a cone-rod dystrophy as well as displayed mislocalization of cone-specific proteins such as OPN1SW, OPN1MW and GNAT2; we report that OPN1MW and GNAT2 are mislocalized in Bbs10−/− mice." (PMID 36125046, 2022).
retinitis pigmentosa (3 papers, 2020 to 2022). Retinitis pigmentosa (RP) is an inherited retinal dystrophy leading to progressive loss of the photoreceptors and retinal pigment epithelium and resulting in blindness usually after several decades. "As expected, expression levels for the cone-specific genes Opn1sw, Opn1mw, and Gnat2 in the Rds mutant retinas at P25 did not deviate from wild type levels since cone degeneration is delayed in this retinitis pigmentosa model." (PMID 32313077, 2020).
retinal degeneration (2 papers, 2015 to 2019). Degeneration of the retina. "We screened the mutant Pde6brd1 (c.1041C > A) allele, two mutant alleles in the Gnat2 gene, Gnat2 (c.518A>G) and Gnat2Cpfl3 (c.598G>A), and the polymorphism in the Rpe65 gene, RPE65Met450Leu [Rpe65 (c.1348C>A)], that has been previously shown to be a genetic modifier for retinal degeneration." (PMID 25147295, 2015).
depression (1 paper, 2021). "We detected high impact variants in genes previously implicated in depression (e.g. Gnat2), depression-like behavior (e.g. Prlr, Nlrp1a), other psychiatric disease (e.g. Pou6f2, Kdm5a, Reep3, Wdfy3), and responses to psychological stressors (e.g. Pigr)." (PMID 34285244, 2021).
retinal disease (1 paper, 2017). "Moreover, GNAT2 and OPN1SW are cone-specific markers, and the dysregulation of these genes may be related to retinal disease." (PMID 28484645, 2017).
GNAT2 also shares sentences with these, for which no sentence is quoted: myopia (2 papers); Blindness (1); cataract (1); diabetic retinopathy (1); macular degeneration (1); microphthalmia (1); night blindness (1); oligocone trichromacy (1); protanopia (1); psychiatric disease (1); red-green color blindness (1); Refsum disease (1); Stargardt disease (1); unipolar depression (1); Usher syndrome (1).